IL33 (interleukin 33)
Diseases named in the same sentence as IL33 in open-access papers (continued):
Sharing a sentence is not in itself a finding about the gene and the disease.
kidney failure (6 papers, 2016 to 2024). An acute or chronic condition that is characterized by the inability of the kidneys to adequately filter the blood. "Both LoCHO_PROT and LoCHO_FAT decreased IL-33, and their role in managing or attenuating kidney failure is warranted." (PMID 38590952, 2024). "All in all, in the future, serum levels of IL-33 immediately after reperfusion could be integrated in multiparametric prognostic tools such as MEAF score to predict graft function and posttransplant kidney failure." (PMID 34621275, 2021). "However, the IL-33 levels in MM patients with kidney failure were not statically significantly different in MM patients who did not have kidney failure." (PMID 28387719, 2017).
liver failure (6 papers, 2015 to 2022). A liver disease characterized by the liver losing or has lost all of its function. "Imbalances in the Th1/Th2 response were first observed in the hepatic pathogenesis, and it was shown that IL-33/ST2 is upregulated in hepatic failure." (PMID 35056005, 2022). "A recent study reported that the elevated level of IL-33 was observed in patients with liver failure and the IL-33 level correlated with its decoy receptor soluble ST2 level and alanine aminotransferase (ALT) activity." (PMID 25892853, 2015). "A previous study provided evidence for elevated levels of IL-33 and soluble ST2 in liver failure, which could be a sign of immune hyperactivation, and/or a mechanism to down-regulate inflammation." (PMID 27180842, 2016).
lymph node metastasis (6 papers, 2016 to 2022). "With a more malignant factor, the serum IL-33 got a higher level and was associated with the tumor stages (P = 0.035), depth of invasion (P = 0.008), distant metastasis (P = 0.014), and lymph node metastasis (P = 0.029)." (PMID 27340318, 2016). "Furthermore, TTP RNA and protein levels were remarkably reduced in GC and inversely correlated with IL-33 level, and they were also closely associated with depth of invasion, lymph node metastasis, advanced TNM stage, as well as survival rate." (PMID 27074834, 2016). "At a high TNM stage (stage III) and lymph node metastasis (N1‐3), the expressions of IL‐33 and CD206 were significantly upregulated (P < .05)." (PMID 33305406, 2021). "In our study, the serum IL-33 is commonly elevated accompanied with some serious clinical factors, like higher tumor stages, depth of invasion, and existence of lymph node metastasis and distant metastasis, which may be further suggested to be related to the progress of the adenocarcinoma." (PMID 27340318, 2016).
lymphoma (6 papers, 2018 to 2023). A malignant (clonal) proliferation of B- lymphocytes or T- lymphocytes which involves the lymph nodes, bone marrow and/or extranodal sites. "A mouse model of lymphoma was used to test the ability of IL-33 to enhance γδ anti-cancer cell therapy." (PMID 30205617, 2018). "It was reported that local IL-33 production could inhibit the tumor growth of a lymphoma cell line, by recruiting eosinophils into tumors through the overproduction of IL-5 from the IL-33-driven ILC2s." (PMID 33233582, 2020). "IL-33 expands anti-lymphoma Vγ9 T cells and improves the therapeutic response to phosphoantigen." (PMID 30483263, 2018).
Miscarriage (6 papers, 2016 to 2026). A pregnancy that ends at a stage in which the fetus is incapable of surviving on its own, defined as the spontaneous loss of a fetus before the 22th week of pregnancy. "In interventional studies, senotherapies with metformin or dasatinib plus quercetin restored placental development and improved pregnancy outcomes in both IL33-deficient and inflammation-induced miscarriage models." (PMID 41975562, 2026). "Previous reports have associated interleukin IL-33 with miscarriage, fetal damage, and premature delivery due to infections with various microorganisms." (PMID 39065188, 2024). "In later study, more experiments are also needed to elucidate the association of serum IL-33 levels between pre-pregnancy with post-pregnancy in idiopathic recurrent miscarriage patients." (PMID 27026387, 2016). "However, high maternal serum IL33 levels are associated with miscarriage." (PMID 37664846, 2023). "Yue notes that IL-33 serum levels are significantly lower in idiopathic recurrent miscarriage cases than in the control group." (PMID 39035635, 2024). "Above data suggest that dysregulated levels of serum IL-33 indicate miscarriage in live early pregnancies." (PMID 27026387, 2016). "IL-33 and sST2 may become novel biomarkers for early prediction of pregnancy failure and recurrent miscarriage, providing potential new targets for the treatment of RSA." (PMID 35095557, 2021). "We also statistically analyzed whether the elevated serum IL-33 and sST2 were related to number of miscarriage in diseased group." (PMID 35095557, 2021). "Although IL-33 plays an exact role in embryo-maternal interactions, especially during early stages of implantation, our data support the notion that miscarriage may be attributed, at least in part, to low level of IL-33 expression and secretion." (PMID 27026387, 2016). "However, the mean IL-33 serum level was slightly lower in women with a history of recurrent miscarriage, which could be a significant difference in larger samples due to the limited sample size in this study." (PMID 39035635, 2024).
oral squamous cell carcinoma (6 papers, 2020 to 2026). "There is evidence that lncRNA FLJ22447 expression is upregulated in tumor-associated stromal fibroblasts of oral squamous cell carcinoma, stabilizing IL-33 by inhibiting the autophagic lysosomal pathway, thereby promoting tumor cell proliferation." (PMID 35004889, 2021). "As another example, lncRNA-CAF induce transition from normal fibroblasts to CAFs by stabling IL-33, thereby leading to development of oral squamous cell carcinoma." (PMID 33665192, 2021). "For instance, Lnc-CAF reprograms fibroblasts to promote the growth of oral squamous cell carcinoma via p62-dependent autophagy-lysosome degradation of IL-33 and a-SMA/Ki67 upregulation." (PMID 32754302, 2020). "In patients with oral cavity squamous cell carcinoma (OCSCC), the high expression of IL-33 in tumor samples seemed to be associated with favorable OS, as shown by the survival curves, although without statistical significance (p = 0.473)." (PMID 33634017, 2020). "In oral cavity squamous cell carcinoma (OCSCC), IL-33 may act as an anti-tumour factor." (PMID 38662248, 2024).
peanut allergy (6 papers, 2017 to 2024). "In 2019, the results of phase two of a randomized, placebo-controlled study of anti-IL-33 (etokimab) in peanut allergy were found." (PMID 34301307, 2021). "The importance of EC-derived IL-33 for in vivo DC activation was demonstrated using a murine model for intragastric induced peanut allergy." (PMID 28507730, 2017). "Murine studies revealed that increased epithelial IL33 secretion is sufficient for in vivo DC activation leading to peanut allergy, independent of IL25 and TSLP." (PMID 36700233, 2022). "Epithelium-derived factors (IL-33, TSLP, IL-25) identified in studies focusing on HDM-induced sensitization were observed during\ intestinal peanut sensitization in mice, of which it was shown that IL-33 is important for OX40L expression on DC and the development of peanut allergy (see KE 2)." (PMID 28507730, 2017).
pulmonary hypertension (6 papers, 2017 to 2026). Increased pressure within the pulmonary circulation due to lung or heart disorder. "Administration of IL-33 in vivo exacerbates hypoxia-induced pathological changes associated with pulmonary hypertension in wild type mice." (PMID 32903501, 2020). "The IL‐33/ST2 pathway is essential for the early endothelial cell proliferative response in Sugen/hypoxia‐induced pulmonary hypertension that leads to remodeling of the small resistance pulmonary arteries." (PMID 35150208, 2022). "In a mouse model of hypoxia-induced pulmonary hypertension exogenous IL-33 aggravated pulmonary hypertension that was evident by elevation of the mean right ventricular systolic pressure and right ventricular hypertrophy index." (PMID 34948083, 2021).
respiratory infection (6 papers, 2020 to 2024). "Although S. aureus may cause respiratory infections, isolation of S. aureus from the adapted environment of AR nasal mucus reduced Th2 inflammation by suppressing IL-33 expression in allergic nasal epithelium." (PMID 33028252, 2020). "So far, IL-33 signaling was more studied in the respiratory system and found to modulate IL-22-dependent antibacterial defense during respiratory infection." (PMID 38533053, 2024). "For example, in children with acute lower respiratory infection (ALRI), local activation of the IL-33/ST2 axis has been shown to be associated with a more severe disease evolution, with the need for ventilatory support." (PMID 35327516, 2022). "They evaluated the IL-33/ST2 axis in acute lower respiratory infection in 73 children of less than 5 years of age." (PMID 35327516, 2022). "In fact, IL-33 is known to increase airway inflammation, mucus secretion and Th2 cytokine synthesis in the lungs, following respiratory infections such as influenza virus, RSV and rhinovirus infection." (PMID 35327516, 2022). "IL-33, a key cytokine involved in both innate and adaptive immune responses in mucosal organs, can increase airway inflammation, mucus secretion and Th2 cytokine synthesis in the lungs, following respiratory infections." (PMID 36498859, 2022). "In addition, it was recently described that the administration of IL-33 is capable of increasing the protection of BALB/c mice against respiratory infection by K. pneumoniae." (PMID 35806365, 2022).
retinal detachment (6 papers, 2019 to 2025). An eye emergency condition which may lead to blindness if left untreated. "Additionally, IL-33-deficient mice with retinal detachment show more severe cone photoreceptor degeneration, emphasizing its protective role in retinal health." (PMID 40512033, 2025). "We previously showed that, in a mouse model of retinal detachment, deletion of endogenous IL-33 accelerated the retinal degeneration accompanied by severe retinal inflammation." (PMID 37671525, 2023). "Amongst the altered factors that modulate retinal inflammation, IL-33 has been shown to play a key role in retinal neuron survival in a model of retinal detachment and regulate angiogenesis in laser-induced choroidal neovascularisation." (PMID 37671525, 2023). "Taken together, our data suggest that deletion of IL-33 resulted in persistent retinal gliosis and subretinal inflammation following retinal detachment." (PMID 31796062, 2019). "We also showed that IL-33−/− mice developed more severe retinal degeneration following retinal detachment." (PMID 31796062, 2019). "Retinal detachment resulted in significant reductions in the amplitudes of both A- and B-waves in both strains; however, the reduction in A-wave was more severe in IL-33−/− RD mice compared to that in WT RD mice." (PMID 31796062, 2019). "Previously, we have shown that the protective role of endogenous IL-33 expressed in Müller cells alleviates retinal inflammation, reflected through reduced gliosis, macrophage activation and neurodegeneration in a mouse model of retinal detachment." (PMID 37671525, 2023). "IL-33 may provide a previously unrecognised protective response by negatively regulating macrophage activation following retinal detachment." (PMID 31796062, 2019). "Müller cell gliosis is a critical response during the acute phase of retinal detachment (RD), and in this study, we investigated if IL-33 was modulatory in the inflammatory and neurodegenerative pathology which is characteristic of this important clinical condition." (PMID 31796062, 2019). "IL-33 has demonstrated protective factors in regulating RPE autophagy in macular degeneration and retinal detachment." (PMID 40563988, 2025). "Further, a mouse model lacking the immune suppressing cytokine interleukin-33 (IL-33) was shown to display enhanced retinal degeneration and Müller cells gliosis following retinal detachment." (PMID 38983084, 2023).
rheumatic diseases (6 papers, 2012 to 2022). "The current study constitutes the first report of associations between IL-33 gene polymorphisms and rheumatic diseases in a Caucasian population." (PMID 34177886, 2021). "Nevertheless, additional studies with larger sample sizes and different populations are needed to validate these findings and to establish the exact role of IL-33 polymorphisms in rheumatic diseases." (PMID 34177886, 2021). "Therefore, the role of IL-33/ST2 depends on the underlying pathological conditions in rheumatic diseases." (PMID 34589505, 2021). "A growing number of studies have found that the level of IL-33 is associated with the severity of rheumatic disease, indicating that IL-33 and ST2 may be potential targets for predicting the development of disease and improving the clinical outcomes." (PMID 34589505, 2021). "The results indicated that IL-33 polymorphisms might be associated with rheumatic disease risk and anti-TNF treatment outcomes in Caucasians." (PMID 34177886, 2021). "Furthermore, evidence has indicated that IL-33-related treatment may ameliorate the pathogenic conditions and attenuate disease progression of those rheumatic diseases." (PMID 24151520, 2013). "Although great advances have been made in recent years, more evidence is needed to clarify the exact role of the IL-33/ST2 axis in rheumatic diseases." (PMID 34589505, 2021). "IL-33 can also participate in the pathogenesis of rheumatic disease by interacting with ST2-expressing tissue cells, such as cardiomyocytes, oligodendrocytes, epithelial cells, and endothelial cells." (PMID 34589505, 2021). "In this review, we summarize the role of the IL-33/ST2 axis in rheumatic diseases by summarizing the evidence from clinical patients, mouse models, and in vitro cell culture." (PMID 34589505, 2021). "Recent studies reported the correlation of IL-33 with rheumatic diseases, and most of them found that the IL-33 expression levels were consistent with disease activity and development." (PMID 24151520, 2013). "Taken together, as a novel member of IL-1 family, IL-33 plays an important role in the development and progression of rheumatic diseases." (PMID 24151520, 2013). "So far, investigations on IL-33 and rheumatic diseases mostly focus on the expression level of IL-33 and disease activity, but the underlying mechanism and related clinical therapy still remain to be studied." (PMID 24151520, 2013). "This review focuses on the dual role of the IL-33/ST2 axis in rheumatic diseases." (PMID 34589505, 2021). "Expression and mechanisms of IL-33/ST2 in rheumatic diseases." (PMID 34589505, 2021). "Next, we will discuss the role of the IL-33/ST2 axis in several common rheumatic diseases." (PMID 34589505, 2021). "Moreover, targeting TNF-α, IL-1β, or IL-33 in rheumatic diseases reduce neutrophil recruitment and pain." (PMID 30333752, 2018). "In this paper, we will summarize the roles of IL-33 in the rheumatic diseases." (PMID 24151520, 2013). "Therefore, elucidation of the roles of IL-33 in rheumatic diseases would be beneficial to understand the pathogenesis and therapy of these diseases." (PMID 24151520, 2013). "Therefore, in the progression of rheumatic disease, IL-33 may increase the production of IFN-γ and may amplify the immune effects." (PMID 34589505, 2021). "In general, IL-33/ST2 axis plays a detrimental role in both early and advanced stages of most rheumatic diseases." (PMID 34589505, 2021).
ST Elevation Myocardial Infarction (6 papers, 2012 to 2022). A myocardial infarction that produces elevation in the ST segments of the ECG. "One study showed that sST2 and IL-33 were associated with mortality in patients with ST elevation myocardial infarction (STEMI) but not in patients with non-STEMI (NSTEMI) or stable angina pectoris (SAP)." (PMID 33608010, 2021). "IL-33 serum levels were measured in 387 consecutive patients undergoing percutaneous coronary intervention (PCI) of whom 193 had stable angina, 93 non-ST elevation myocardial infarction (NSTEMI), and 101 ST-elevation MI (STEMI), respectively." (PMID 24725541, 2014). "In contrast to our findings, Dhillon and colleagues reported that IL-33 levels were not correlated with adverse outcomes in non-ST-elevation myocardial infarction (NSTEMI) patients." (PMID 22682001, 2012). "Other recent studies have shown that elevated levels of both sST2 and IL33 were associated with increased mortality in ST elevation myocardial infarction (STEMI), but IL33 did not predict mortality in patients with non-ST elevation myocardial infarction (NSTEMI), or stable angina." (PMID 26544186, 2015). "We assessed the predictive value of sST2 and IL-33 in patients with stable angina, non-ST elevation myocardial infarction (NSTEMI) and ST elevation myocardial infarction (STEMI)." (PMID 24751794, 2014).
stable angina (6 papers, 2013 to 2023). "Both sST2 and IL-33 were associated with mortality in patients with STEMI but not in patients with NSTEMI or stable angina over a period of time of more than 3.5 years." (PMID 24751794, 2014). "sST2 and IL-33 were associated with mortality in patients with STEMI but not in patients with NSTEMI or stable angina." (PMID 24751794, 2014).
vasculitis (6 papers, 2014 to 2025). "To explore the mechanism of these findings in patients, we established a model of EGPA in which active vasculitis and pulmonary hemorrhage were induced by IL-33 administration in predisposed, hypereosinophilic mice." (PMID 33974563, 2021). "While infiltrating cells and vasculitis were seen in the retina of the control WT mice, minimal inflammation was observed in the retina tissue of IL-33-treated WT mice." (PMID 25116404, 2014). "What is particularly promising is the growing evidence that the IL-33/sST2 axis may represent a therapeutic target in KD vasculitis." (PMID 40723060, 2025). "However, we cannot exclude that IL-33 production also characterizes a “healing” stage of vasculitis occurring after the acute phase of inflammation." (PMID 32286393, 2020). "Even during IL-33 administration, ILC2s were the predominant population of IL-5–expressing cells in the mouse lung, indicating that deletion of Th2 cells was unlikely to explain the absence of vasculitis." (PMID 33974563, 2021).